UNC5A (unc-5 netrin receptor A)
Description:
Receptor for netrin required for axon guidance. Functions in the netrin signaling pathway and promotes neurite outgrowth in response to NTN1. It also acts as a dependence receptor required for apoptosis induction when not associated with netrin ligand.
Synonyms: KIAA1976; UNC5H1
Tractability: Antibody: its Gene Ontology location is reachable by antibodies, with high confidence; UniProt places it where antibodies can reach, with medium confidence; UniProt predicts a signal peptide or a membrane-spanning region; the Human Protein Atlas places it where antibodies can reach. PROTAC: its protein half-life has been measured.
Gene: Protein-coding gene on chromosome 5 (176,810,505 to 176,880,898, forward strand). Ensembl gene ENSG00000113763.
Subcellular location: Cell membrane; Membrane raft; Cell projection, neuron projection
Subcellular location (Human Protein Atlas): Cytosol; Plasma membrane
Pathways (Reactome):
Developmental Biology: Netrin mediated repulsion signals; Netrin-1 signaling
Programmed Cell Death: Caspase activation via Dependence Receptors in the absence of ligand
Gene Ontology:
Molecular function: netrin receptor activity
Biological process: anterior/posterior axon guidance; netrin-activated signaling pathway; neuron projection development; signal transduction
Cellular component: membrane raft; neuron projection membrane; neuronal cell body membrane; plasma membrane; membrane; neuron projection
Genetic constraint (gnomAD): Loss-of-function variants: 20 observed, 83.94 expected, observed/expected ratio (o/e) 0.24, 90% interval 0.17 to 0.35. The upper end of that interval is the gene's LOEUF score, 0.35, which puts it in group 1 of 6, group 1 being the genes least tolerant of losing a copy. Missense variants: 839 observed, 1,136.5 expected, observed/expected ratio (o/e) 0.74, 90% interval 0.7 to 0.78. Synonymous variants: 435 observed, 479.31 expected, observed/expected ratio (o/e) 0.91, 90% interval 0.84 to 0.98.
Homologues: Orthologues: chimpanzee UNC5A (99% identical), macaque UNC5A (99% identical), guinea pig UNC5A (98% identical), pig UNC5A (97% identical), dog UNC5A (97% identical), mouse Unc5a (97% identical), rat Unc5a (96% identical), rabbit UNC5A (87% identical), tropical clawed frog unc5a (70% identical), zebrafish unc5a (67% identical), Drosophila melanogaster unc-5 (28% identical), Caenorhabditis elegans unc-5 (27% identical). Paralogues in human: UNC5C (54% identical), UNC5B (52% identical), UNC5D (44% identical), UNC5CL (15% identical).
Diseases named in the same sentence as UNC5A in open-access papers:
UNC5A is named in the same sentence as 55 diseases in open-access papers, as found by Europe PMC text mining. Sharing a sentence is not in itself a finding about the gene and the disease. The quoted sentences say what the papers report.
breast carcinoma (5 papers, 2018 to 2024). "Moreover, studies revealed that Unc5a is associated with many types of cancer and acted as a tumor suppressor in non-small cell lung cancer, may serve as a new early marker in prostate cancer, and restricted the metastasis of breast cancer cells." (PMID 36829196, 2023). "Tissue microarray and immunohistochemistry were utilized to determine the prognostic value of UNC5A in breast cancer." (PMID 29720215, 2018). "Although several studies have reported the role of UNC5A in breast cancer, colorectal cancer, non-small cell lung cancer, bladder cancer, and gliomas, its significance in other human cancers remains unclear." (PMID 36551254, 2022). "Furthermore, UNC5A knockdown cells provide an ideal model system to investigate metastasis of ERα+ breast cancers." (PMID 29720215, 2018). "Thus, UNC5A is a potential biomarker of outcome in a subgroup of breast cancer patients whose tumors express luminal A markers." (PMID 29720215, 2018). "Thus, mutations and DNA methylation could be other mechanisms leading to inactivation/silencing of UNC5A during breast cancer progression." (PMID 29720215, 2018). "Also, analyses of The Cancer Genome Atlas (TCGA) dataset for the relationship between UNC5A expression and breast cancer subtypes using the UALCAN program revealed highest UNC5A expression in luminal breast cancers, which are usually ERα-positive, compared with TNBCs." (PMID 29720215, 2018). "Consistent with this possibility, UNC5A expression was prognostic in ER+/PR+/HER2− breast cancers but not in ER− tumors, suggesting its critical role in ER+/PR+/HER2− breast cancers." (PMID 29720215, 2018). "Analyses of TCGA dataset showed elevated expression of UNC5A in luminal breast cancers, and NTN1 overexpression in TNBCs and E2 could further enhance luminal expression of UNC5A." (PMID 29720215, 2018). "UNC5A and NTN1 are described as tumor suppressor and oncogene, respectively, in breast cancer." (PMID 29720215, 2018). "Therefore, UNC5A, ERα, and EGFR could be developed as markers to identify luminal breast cancers with a potential for subtype conversion." (PMID 29720215, 2018). "Thus, UNC5A could serve as a negative feedback molecule in ERα signaling, the deregulation of which could lead to breast cancer progression through enhanced plasticity." (PMID 29720215, 2018).
glioma (5 papers, 2017 to 2024). A benign or malignant brain and spinal cord tumor that arises from glial cells (astrocytes, oligodendrocytes, ependymal cells). "According to univariate analysis, chemotherapy status, age, grade, IDH mutation status, PRS type, 1p19q codeletion status, UNC5A expression, and histology were all significantly associated with OS in gliomas (all p < 0.05)." (PMID 39039366, 2024). "ScRNA-seq analysis by the CancerSEA online website presented that UNC5A had a low expression in various glioma clusters and significantly associated with six functional states." (PMID 39039366, 2024). "Therefore, in this study, we first combined scRNA-seq, proteomics, and bulk RNA-seq in order to investigate UNC5A's expression, prognosis, associated pathways or drugs, and clinical or immune relevance in gliomas." (PMID 39039366, 2024). "However, little was known about the associations among UNC5A and glioma." (PMID 39039366, 2024). "In both the TCGA and CGGA datasets, gliomas patients with low-UNC5A expression would have poorer overall survival (OS) prognoses." (PMID 39039366, 2024). "By TCGA pan-cancer analysis, we observed that UNC5A’s mRNA expression levels were differentially expressed in various cancers, containing glioma samples of LGG and GBM." (PMID 39039366, 2024). "All in all, UNC5A was found to have prognostic and immunological significance in gliomas, offering patients with gliomas new treatment options." (PMID 39039366, 2024). "According to our results, the TCGA dataset showed a significantly reduced expression of UNC5A by comparing gliomas with normal tissues, which was also confirmed by GSE50161, GSE4290, and QRT-PCR findings." (PMID 39039366, 2024). "Based on multivariate analysis, grade, age, IDH mutation status, chemotherapy status, UNC5A expression, 1p19q codeletion status, and PRS type were all shown to be independent predictors of OS in glioma patients (all p < 0.05)." (PMID 39039366, 2024). "In conclusion, UNC5A was revealed to be a potential biomarker for glioma patients’ OS prognoses, potentially taking part in the progression of glioma via the calcium pathway, the Gnrh pathway, and the JAK-STAT pathway." (PMID 39039366, 2024). "By comparing gliomas with normal tissues, the TCGA dataset showed a significantly reduced expression of UNC5A, which was also confirmed by GSE50161, GSE4290, and QRT-PCR findings (p < 0.05)." (PMID 39039366, 2024). "UNC5A was found to have prognostic and immunological significance in gliomas, offering patients with gliomas new treatment options." (PMID 39039366, 2024). "First, further in vivo and in vitro experiments were necessary to fully understand UNC5A’s activities in gliomas." (PMID 39039366, 2024). "In the GSE4290, GSE50161, and TCGA datasets, our results confirmed that UNC5A was lowly expressed in glioma tissues compared with normal tissues, respectively." (PMID 39039366, 2024). "In both the TCGA and CGGA datasets, gliomas patients with low-UNC5A expression would have poorer overall survival (OS) prognoses (p < 0.05)." (PMID 39039366, 2024). "All of these indicated the prognostic and immunological significance of UNC5A in gliomas, offering patients with gliomas new treatment options." (PMID 39039366, 2024). "Netrin-1 enhances c-Myc expression via NF-κB to promote glioma cell proliferation at least in part via UNC5A." (PMID 28710382, 2017). "ROC curves indicated a moderate diagnosis power of UNC5A in gliomas with AUC values of 0.714." (PMID 39039366, 2024). "Therefore, we first combined scRNA-seq, proteomics, as well as bulk RNA-seq in order to investigate UNC5A’s functions in gliomas." (PMID 39039366, 2024). "Online databases provided scRNA-seq, proteomics, as well as bulk RNA-seq data on UNC5A in gliomas." (PMID 39039366, 2024). "At present, there was still a gap in the researches about the roles of UNC5A in glioma." (PMID 39039366, 2024). "These all demonstrated the possible functions of the three UNC5A-related pathways in gliomas." (PMID 39039366, 2024).
glioma (continued). "Based on the results of GSEA, UNC5A might be connected to three significant pathways in gliomas, including the calcium pathway, the Gnrh pathway, and the Jak-stat pathways." (PMID 39039366, 2024). "Furthermore, UNC5A mRNA levels were substantially reduced in glioma U251 cells, as demonstrated by QRT-PCR data." (PMID 39039366, 2024). "In order to give a quantitative way for predicting the 1-, 3-, and 5-year OS rates in glioma patients, we also created a Norman chart incorporating UNC5A expression and clinicopathological characteristics, evaluating it by calibration plots, C-index, and ROC curves." (PMID 39039366, 2024). "The TSNE plot showed that UNC5A was lowly expressed in various glioma clusters." (PMID 39039366, 2024). "Taken together, these results suggested netrin-1 promotes glioma cell proliferation by activating NF-κB signaling via UNC5A, netrin-1 may be a potential therapeutic target for the treatment of glioma." (PMID 28710382, 2017). "We found that UNC5A had a reasonable expression level in the tested glioma cells and glioma patients, suggesting it may mediate the cellular effects of netrin-1 in glioma." (PMID 28710382, 2017). "Therefore, we have theorized that netrin-1 activates NF-κB via UNC5A to promote glioma cell proliferation." (PMID 28710382, 2017). "Finally, in this article, UNC5A was measured by sequencing the glioma tumor biopsy." (PMID 39039366, 2024). "Based on the results of GSEA, UNC5A might be connected to three significant pathways in gliomas." (PMID 39039366, 2024). "In order to acquire an understanding of how UNC5A contributes to the growth of gliomas, GSEA was conducted by us, and three signaling pathways involved with UNC5A in gliomas were identified: the calcium pathway, the GnRh pathway, and the Jak-stat pathway." (PMID 39039366, 2024). "Moreover, UNC5A might be a reliable independent biomarker of OS in gliomas patients." (PMID 39039366, 2024). "Moreover, UNC5A might be a reliable independent biomarker of OS in gliomas patients (p < 0.05)." (PMID 39039366, 2024). "Differentially expressed genes (DEGs) in the glioma samples relative to normal samples were screened from the GEO database, and five prognostically relevant BM-related genes, including NELL2, UNC5A, TNC, CSPG4, and SMOC1, were selected using Cox regression analyses for the risk score model." (PMID 36292695, 2022). "Nevertheless, not much research has been done on UNC5A in gliomas up to this point." (PMID 39039366, 2024).
colon cancer (3 papers, 2018 to 2022). "The tumor-suppressing role of UNC5A has also been confirmed in other cancer types, including bladder cancer and colon cancer." (PMID 36551254, 2022). "In our hands, O-GlcNAcylation does not seem to affect either stability or catalytic activity of EZH2 but appears to regulate the binding of EZH2 at specific loci including the UNC5A promoter in colon cancer cells." (PMID 33126652, 2020). "Taken together, these results demonstrate that O-GlcNAcylation regulates the PRC2-mediated repression of UNC5A in human colon cancer cells." (PMID 33126652, 2020). "Recently, studies have found that UNC5A plays an important role in multiple cancers, such as bladder cancer, non-small cell lung carcinoma, and colon cancer but its pan-cancer function is largely unknown." (PMID 36551254, 2022). "Next, we wondered whether the PRC2 complex was also involved in the regulation of UNC5A transcription in colon cancer cells." (PMID 33126652, 2020). "To evaluate the role of O-GlcNAcylation in the epigenetic downregulation of the UNC5 family, we first examined the expression of UNC5A, UNC5B, UNC5C and UNC5D transcripts in the human colon cancer cell line HCT116." (PMID 33126652, 2020). "So, taken together, our overall results demonstrate that in colon cancer cells, O-GlcNAcylation of EZH2 targets the PRC2 complex onto the UNC5A promoter to inhibit its transcription." (PMID 33126652, 2020). "Mechanistically, we provide evidences that the O-GlcNAcylated form of EZH2 prevents the transcription of UNC5A in human colon cancer cells through aberrant O-GlcNAcylation and abnormal targeting of the PRC2 complex onto its promoter, thus linking nutrition to downregulation of UNC5A in CRC." (PMID 33126652, 2020). "However, we observed elevated expression of ITGB6 (Integrin β6) in sh-UNC5A cells compared with sh-Control cells; ITGB6 is pro-oncogenic and is induced during EMT of colon cancer cells." (PMID 29720215, 2018). "However, the involvement of this OGT-EZH2 axis in the regulation of the expression of UNC5A as well as the other members of the UNC5A family in colon cancer cells has not been studied." (PMID 33126652, 2020).
colorectal cancer (3 papers, 2010 to 2022). A primary or metastatic malignant neoplasm that affects the colon or rectum. "In fact, expression of UNC5A, UNC5B and UNC5C is frequently downregulated in colorectal cancer (CRC) and their silencing has been associated in part with loss of heterozygoty (LOH) within UNC5 loci and with epigenetic alterations that are not fully understood." (PMID 33126652, 2020). "Whereas DCC (Deleted in colorectal cancer) alone can mediate Netrin-dependent attraction, Unc5a can function alone or with DCC to mediate repulsion." (PMID 20569485, 2010).
neuroblastoma (3 papers, 2019 to 2023). Neuroblastoma (NB) is the most common solid, extracranial childhood tumor. "Surprisingly, as opposed to its well reported repulsive role, overexpression of Unc5a in N1E-115 neuroblastoma cells has been shown to induce neurite outgrowth by increasing Rac1 and Cdc42 activity." (PMID 30934641, 2019). "Moreover, it has also been reported that Unc5a-overexpressing N1E-115 neuroblastoma cells lead to transient Rac1 activation in early stages and RhoA activation in the later stages of neurite outgrowth." (PMID 30934641, 2019). "In human neuroblastoma SH-SY5Y cells differentiated into neurons, Unc5A was required for robust neurite outgrowth." (PMID 37649551, 2023).
COVID-19 (2 papers, 2022 to 2025). A disease caused by infection with severe acute respiratory syndrome coronavirus 2. "We found higher immune infiltrations of M0 macrophages and neutrophils and significantly elevated levels of DUSP13 and UNC5A in COVID-19." (PMID 36140771, 2022). "Samples with higher scores tended to have a higher probability of COVID-19, and significantly higher expressions of CLEC4D, DUSP13, and UNC5A were found in COVID-19 patients compared with those in healthy controls in GSE152641 and GSE171110." (PMID 36140771, 2022). "Finally, a three-gene signature comprising CLEC4D, DUSP13, and UNC5A that can accurately distinguish COVID-19 patients and healthy controls in three datasets was constructed." (PMID 36140771, 2022). "In conclusion, we constructed a three-gene signature to identify COVID-19, and CLEC4D, DUSP13, and UNC5A may be potential biomarkers for COVID-19 patients." (PMID 36140771, 2022).
glioblastoma (2 papers, 2022 to 2024). The most malignant astrocytic tumor (WHO grade IV).
ischemic stroke (2 papers, 2023 to 2025). A stroke disorder caused by obstruction of blood flow to the brain, due to thrombotic (local blood clot formation) or embolic (due to a blood clot or other material traveling from another site) event. "Previous studies have shown microglial expression of netrin-1 and UNC5a in clinical patients during an ischemic stroke and in rodent models of experimental ischemic stroke." (PMID 40723793, 2025). "Therefore, our results suggest that cerebral microglia from experimental rodents with ischemic stroke exhibit an increased expression of Netrin-1 and its receptor UNC5a." (PMID 37388740, 2023).
lung carcinoma (2 papers, 2021 to 2022). "Moreover, they knocked down the UNC5A gene in human lung cancer cell lines and found enhanced cellular proliferation, invasion, migration, and apoptosis, while UNC5A overexpression derived opposite outcomes." (PMID 36551254, 2022). "The expression of UNC5A, UNC5B, or UNC5C is down-regulated in multiple cancers including lung cancer, and UNC5B has also been indicated as a putative tumor suppressor." (PMID 33711952, 2021).
non-small cell lung carcinoma (2 papers, 2022 to 2023). A group of at least three distinct histological types of lung cancer, including non-small cell squamous cell carcinoma, adenocarcinoma, and large cell carcinoma. "For instance, Silu Ding and colleagues found lowered UNC5A expression levels in non-small cell lung carcinoma compared to adjacent normal tissues." (PMID 36551254, 2022).
thymoma (2 papers, 2019 to 2022). A neoplasm arising from the epithelial cells of the thymus. "UNC5A expression correlated positively with TMB in various cancer types such as COAD, thymoma (THYM), and PCPG, while negatively with LGG, BRCA, STAD, HNSC, cervical squamous cell carcinoma and endocervical adenocarcinoma (CESC), and LIHC." (PMID 36551254, 2022). "In partial contrast, Netrin‐1 receptor antibodies (DCC plus UNC5A, or DCC alone) coexisted with both CASPR2 and LGI1 antibodies in two patients with Morvan syndrome and thymoma recurrence." (PMID 30714278, 2019).
Alzheimer disease (1 paper, 2018). A progressive, neurodegenerative disease characterized by loss of function and death of nerve cells in several areas of the brain leading to loss of cognitive function such as memory and language. "Furthermore, significant expression changes in UNC5A were found in the posterior cingulate brain region of AD patients, while mutations in UNC5C seemed to predispose to late-onset Alzheimer’s disease." (PMID 30213274, 2018).
B-cell neoplasm (1 paper, 2022). A group of heterogeneous lymphoid tumors generally expressing one or more B-cell antigens or representing malignant transformations of B-lymphocytes. "For instance, UNC5A had a relatively high alteration frequency in KIRC (nearly 8%), while no related alterations were found in CHOL, mature B-cell neoplasms, miscellaneous neuroepithelial tumors, seminoma, thymic epithelial tumor, and ocular melanoma." (PMID 36551254, 2022).
bladder urothelial carcinoma (1 paper, 2022). "Kaplan-Meier curves exhibited that patients with high UNC5A expression had worse OS than those with low UNC5A levels in bladder urothelial carcinoma (BLCA), KIRC, LAML, LUSC, and LIHC." (PMID 36551254, 2022).